HIF1A (hypoxia inducible factor 1 subunit alpha)
Diseases named in the same sentence as HIF1A in open-access papers (continued):
Sharing a sentence is not in itself a finding about the gene and the disease.
ovarian carcinoma (332 papers, 2008 to 2026). A malignant neoplasm originating from the surface ovarian epithelium. "In contrast, HIF-1α expression in specific types of tumors is entirely dependent on oxygen-deficiency within the tumor, such as cervical and ovarian cancer." (PMID 40809031, 2025). "Chronic inflammation mediated by HIF-1α pathways is associated with endometriosis-like conditions in patients with ovarian cancer." (PMID 40136686, 2025). "miR-210 expression is upregulated in response to hypoxia in epithelial ovarian cancer specimens and cell lines, with an association to HIF-1α overexpression." (PMID 41357522, 2025). "Ovarian cancer has a substantial effect on female reproductive health, with HIF-1α serving a critical function in the mechanisms associated with infertility." (PMID 40136686, 2025). "Further investigations are needed to clarify the underlying mechanism by which HIF-1α induces MIR210HG expression in ovarian cancer." (PMID 34900667, 2021). "The expression of CCL28 has been found to correlate with HIF-1α expression in ovarian cancer and is associated with poor patient prognosis." (PMID 33923305, 2021). "Previous studies have shown that HIF-1α overexpression in ovarian cancer was associated with poor overall survival." (PMID 34630078, 2021). "The expression of endogenous miR-155-5p increased after being treated with miRNA combination nanoparticles caused decreased HIF1α expression in SKOV3 ovarian cancer cells." (PMID 32986358, 2020). "The up-regulation of TWIST by HIF-1α was also found among clinical samples of ovarian epithelial cancers and was associated with lower overall survival rate." (PMID 32322559, 2020). "In ovarian cancer, we observed an association of elevated HIF-1α, MDR1 and LAPTM4B expression with advance tumor stage, metastasis and pre-treated." (PMID 30746305, 2019). "Based on these observations, we aimed to elucidate the role of HIF-1α in mediating the association between Rab25 expression and the aggressive and tumourigenic phenotype of ovarian cancer cells." (PMID 26967059, 2016). "HIF-1α is highly expressed in ovarian cancer and is associated with tumour proliferation, invasion and metastasis." (PMID 25491408, 2014). "LOX and HIF-1α proteins are both overexpressed in ovarian cancer cells and the expression is significantly associated with advanced clinical stages and metastasis in EOC." (PMID 23545606, 2013). "Overexpression of HIF‐1α has been detected in numerous types of human cancers, and this protein is linked to malignant progression and poor prognosis in cancers such as small cell lung cancer, ovarian cancer, and tongue squamous cell carcinoma." (PMID 41427004, 2025). "However, further studies are needed to fully elucidate the molecular mechanisms underlying the roles of CRABP2 and HIF1α in ovarian cancer." (PMID 38195606, 2024). "HIF-1α has been associated with tumor angiogenesis and ovarian cancer aggressiveness." (PMID 36230617, 2022). "However, further investigations are needed to clarify the underlying mechanism by which HIF-1α induces MIR210HG expression in ovarian cancer." (PMID 34900667, 2021). "Moreover, miR-199 encoded by the antisense strand of DNM2, decreased HIF1α and HIF2α expression leading to the reduction of cell migration and invasion, thus establishing the connection between hypoxia and endocytosis in ovarian cancer." (PMID 33240194, 2020). "Moreover, this study demonstrated that in ovarian cancer samples, the levels of HIF-1α were strongly associated with VM formation and the expression of Twist1, Slug, and Vimentin." (PMID 31612116, 2019). "This suggests that AEG-1 and HIF-1α are potential early diagnostic markers for ovarian carcinoma." (PMID 29770329, 2018).
ovarian carcinoma (continued). "The effect of hCG induction on VM in ovarian cancer cells is potentially associated with HIF-1α." (PMID 27346985, 2016). "The upregulation of Twist2 is associated with HIF-1α expression in ovarian cancer." (PMID 23946798, 2013). "Twist2 increased in epithelial ovarian cancers associated with HIF-1α expression." (PMID 23946798, 2013). "We observed that the frequency of nuclear expression of HIF-1α in benign tumours was lower than in borderline and ovarian cancer tumours, which is in agreement with previous findings and supports the assertion that HIF-1α can be considered a hallmark of tumour progression in ovarian carcinomas." (PMID 19014607, 2008). "In other gynecological malignancies—ovarian cancer, we also observed differences in HIF1A and VEGFA expression levels in a case–control study, but also EPAS1 differed significantly." (PMID 39888575, 2026). "Through the IL‐6/STAT3/HIF‐1α feedback loop, IL‐6 aggravates cisplatin resistance in ovarian cancer cells." (PMID 40968783, 2026). "In ovarian cancer, hypoxia leads to the activation of HIF1α in both tumor cells and CAFs, which triggers the secretion of profibrotic and proangiogenic cytokines such as TGFβ and VEGF, thereby promoting stromal remodeling and neovascularization." (PMID 40968783, 2026). "The current study reported that HIF1α and TFE3 were implicated in the utilization of SHMT2 alternative promoter, resulting in expression of SHMT2 isoforms in cisplatin-resistant ovarian cancer cells under metabolic stress." (PMID 40097394, 2025). "Hypoxia-Inducible Factor-1α (HIF-1α) is integral to the progression of ovarian cancer, facilitating angiogenesis, metabolic reprogramming, epithelial-to-mesenchymal transition, and resistance to therapy." (PMID 40136686, 2025). "Multiple compounds that target HIF-1α via distinct mechanisms have been identified, providing therapeutic advantages in ovarian cancer." (PMID 40136686, 2025). "Excessive hypoxia resulting from HIF-1α overexpression in ovarian cancer disrupts the balance, impairing folliculogenesis and reducing ovarian reserve." (PMID 40136686, 2025). "Nanoparticle-based drugs enhance specificity and efficacy in targeting HIF-1α, offering a dual benefit in the management of ovarian cancer progression while protecting female fertility." (PMID 40136686, 2025). "In the hypoxic microenvironment of ovarian cancer, HIF-1α upregulates endothelial cell-specific molecule 1 (ESM1), which induces PKM2 SUMOylation and stabilizes its dimeric conformation." (PMID 40842995, 2025). "In ovarian cancer, HIF-1α upregulates endothelial cell-specific molecule 1 (ESM1), which enhances PKM2 SUMOylation and stabilizes its dimeric form." (PMID 40842995, 2025). "Inhibiting HIF-1α with targeted agents offers a dual therapeutic strategy that effectively reduces ovarian cancer proliferation while safeguarding reproductive health." (PMID 40136686, 2025). "Previous studies in non-small cell lung cancer (NSCLC) and ovarian cancer have shown that hypoxia promotes downstream gene transcription through the HIF-1α pathway, which contributes to cisplatin resistance." (PMID 41199784, 2025). "Examining the role of HIF-1α in infertility is crucial for formulating targeted interventions to address reproductive dysfunction in women with ovarian cancer." (PMID 40136686, 2025). "This review seeks to clarify the molecular basis of HIF-1α in ovarian cancer and its effects on female infertility, providing insights into novel treatment approaches that target both controlling the disease and preserving fertility." (PMID 40136686, 2025). "Nanoparticle-based drugs for potential therapeutic approaches targeting HIF-1α in ovarian cancer control and female infertility." (PMID 40136686, 2025).
ovarian carcinoma (continued). "In conclusion, these findings suggest a regulatory mechanism in which TRPM7 modulates cellular metabolic shifts in ovarian cancer by influencing the AMPK/HIF-1α signaling pathway, highlighting its role as a key mediator in metabolic reprogramming." (PMID 40813985, 2025). "NAC has demonstrated the ability to suppress HIF-1α activity, inhibit tumor growth, and enhance chemosensitivity in ovarian cancer." (PMID 40136686, 2025). "PX-478 inhibits angiogenesis and therapy resistance by reducing HIF-1α levels, thereby effectively suppressing the growth of ovarian cancer." (PMID 40136686, 2025). "Oxidative stress significantly results from HIF-1α overexpression in ovarian cancer and is essential in ovarian dysfunction." (PMID 40136686, 2025). "Hypoxia, a common event in the ovarian cancer microenvironment, activates HIF-1α, which induces the expression of key EMT genes such as SNAIL, SLUG, and TWIST, and promotes angiogenesis, increasing the tumor’s capacity for invasion and migration." (PMID 40362280, 2025). "In ovarian cancer, NEK6 overexpression is associated with adverse outcomes and drug resistance, possibly through its cooperation with HIF-1α." (PMID 41154634, 2025). "CCL2 released by omental adipocytes facilitates the migration and omental metastasis of ovarian cancer through the activation of PI3K/AKT/mTOR followed by an increase in HIF-1α and vascular endothelial growth factor A (VEGF-A)." (PMID 40076892, 2025). "Nanoparticle-based drug delivery offers an innovative and efficient method for targeting HIF-1α in the treatment of ovarian cancer, while also addressing issues related to female infertility." (PMID 40136686, 2025). "Inhibitors of HIF-1α present potential therapeutic strategies for targeting HIF-1α in the management of ovarian cancer and female infertility." (PMID 40136686, 2025). "HIF-1α is crucial in the pathogenesis of ovarian cancer, facilitating angiogenesis, metabolic reprogramming, EMT, and resistance to therapy." (PMID 40136686, 2025). "Bioinformatics analysis demonstrated that EGCG affects NFκB1, Bcl-2, HIF-1α, MMP, etc., thereby reducing the risk of ovarian cancer." (PMID 41487287, 2025). "In ovarian cancer, elevated HIF-1α levels can modify the ovarian vascular network, resulting in compromised blood supply to follicles and heightened oxidative stress, ultimately diminishing ovarian reserve and oocyte quality." (PMID 40136686, 2025). "Studies indicate that lactic acid enhances HIF1α stability in tumor-associated endothelial cells, subsequently inducing the expression of VEGF, which facilitates angiogenesis in ovarian cancer." (PMID 41561760, 2025). "NAC nanoparticles restore redox balance and inhibit HIF-1α signaling, thereby enhancing chemosensitivity in ovarian cancer cells." (PMID 40136686, 2025). "Despite increasing evidence connecting HIF-1α to ovarian cancer and infertility, notable research gaps persist in elucidating its specific molecular mechanisms and potential therapeutic interventions." (PMID 40136686, 2025). "Dysregulation of HIF-1α in ovarian cancer disrupts hormonal homeostasis, resulting in reproductive dysfunction." (PMID 40136686, 2025). "The integration of HIF-1α-targeted nanoparticles with antioxidant therapy and reproductive medicine has the potential to significantly alter treatment paradigms for ovarian cancer as nanomedicine advances." (PMID 40136686, 2025). "The HIF-1α signaling pathway promotes ovarian cancer growth through the augmentation of angiogenesis, metabolic reprogramming, epithelial–mesenchymal transition (EMT), chemoresistance, and immune evasion." (PMID 40136686, 2025). "PLA analyze confirmed the enhanced interaction of TFE3 and HIF1α in cisplatin-resistant ovarian cancer cells under the low-glucose and hypoxic condition." (PMID 40097394, 2025).
ovarian carcinoma (continued). "HIF-1α is crucial in the regulation of oxidative stress responses, with its overactivation in ovarian cancer resulting in an accumulation of excessive reactive oxygen species (ROS)." (PMID 40136686, 2025). "Selenium-based nanoparticles demonstrate antioxidant and anti-inflammatory effects, modulating HIF-1α pathways in ovarian cancer." (PMID 40136686, 2025). "Hypoxia-Inducible Factor-1α (HIF-1α) is crucial in the progression of ovarian cancer, especially in influencing its tumor microenvironment and promoting pathogenic pathways that worsen female infertility." (PMID 40136686, 2025). "Due to its dual function in ovarian cancer growth and infertility, HIF-1α is a potential therapeutic target." (PMID 40136686, 2025). "Meanwhile, it is well documented that in ovarian cancer, upregulation of HIF-1α and VEGF-A correlates with tumour angiogenesis, aggressiveness and poor prognosis." (PMID 41463127, 2025). "Chronic inflammation significantly contributes to the progression of ovarian cancer and infertility, with HIF-1α serving a pivotal role in the enhancement of pro-inflammatory cytokine production." (PMID 40136686, 2025). "Previous studies have shown that adipocyte-derived IL-6 activates hypoxia-inducible factor 1-alpha (HIF1α) in ovarian cancer, leading to increased tumor cell glycolysis." (PMID 40616161, 2025). "Targeting HIF-1α and its downstream pathways constitutes a viable approach for enhancing treatment outcomes in ovarian cancer." (PMID 40136686, 2025). "In hypoxic conditions, common in ovarian cancer, M2 TAMs produce IL-1β, which activates HIF-1α in tumor cells, creating a feedback loop that enhances EMT." (PMID 40362280, 2025). "The incorporation of HIF-1α inhibitors into clinical practice offers promising prospects for enhancing ovarian cancer outcomes while protecting fertility." (PMID 40136686, 2025). "The relationship between ovarian cancer progression and infertility via HIF-1α signaling underscores the necessity for targeted therapeutic interventions." (PMID 40136686, 2025). "For example, BHS inhibited cisplatin resistance in ovarian cancer by suppressing autophagy via downregulating the HIF‐1α/ATG5 axis." (PMID 39051750, 2024). "In drug-resistant ovarian cancer cells, knocking down HIF1α can block the resistance of CRABP2 to chemotherapy drugs in ovarian cancer cells." (PMID 38195606, 2024). "In ovarian cancer, the HIF-1α-driven NF-κB pathway is responsible for inducing CSC properties through SIRT1 upregulation." (PMID 38424190, 2024). "Studies on ovarian cancer cell lines HO-8910 and A2780 show that HIF-1α upregulates SLC2A12 under hypoxia, impacting GSH metabolism and inhibiting ferroptosis, thus promoting cancer progression." (PMID 39061859, 2024). "The deterioration of the G2 arrest under the hypoxic environment of 1% O2 has also been validated in SKOV3 human ovarian cancer cells following treatment with Paclitaxel, postulating the inhibition of the Src/Stat3/HIF-1α pathway as a potential mechanism." (PMID 39684302, 2024). "CRABP2 affects the sensitivity of ovarian cancer cells to chemotherapy drugs by increasing the overall metabolic level in these cells, and by regulating the expression of HIF1α." (PMID 38195606, 2024). "For example, BHS synergistically interacted with cisplatin to chemosensitise ovarian cancer by suppressing autophagy via downregulating the HIF‐1α/ATG5 axis." (PMID 39051750, 2024). "HOTTIP is also highly expressed in ovarian cancer cells and can promote the development of ovarian cancer and metastasis of ovarian cancer cells by regulating the transcription factor HIF-1α or pyroptosis." (PMID 39027044, 2024). "Taken together, our findings suggest for the first time that CRABP2 affects chemotherapy resistance of ovarian cancer by regulating the expression of HIF1α." (PMID 38195606, 2024).
ovarian carcinoma (continued). "Our results showed that HIF1α is indeed highly expressed in ovarian cancer-resistant cells, and knocking down the expression of CRABP2 led to a decrease in both HIF1 protein and RNA levels." (PMID 38195606, 2024). "Recently, we have confirmed the formation of IL-6/STAT3/HIF-1α autocrine signaling loop in ovarian cancer cells in vitro and in vivo, which confers chemoresistance against cisplatin to ovarian cancer." (PMID 36814597, 2023). "Enhanced activation of AMPK in ovarian cancer inhibits aerobic glycolysis and promotes the degradation of HIF-1α ubiquitination." (PMID 36937390, 2023). "Hypoxia-inducible factor (HIF)-1α activates WTAP transcription causing enhanced proliferation and migration of ovarian cancer in vitro, and WTAP targets DGCR8 in an m6A-modified manner to promote maturation of precursor miRNAs." (PMID 37194218, 2023). "In order to interrogate the effects of CoCl2 exposure on HIF-1α protein levels, primary ovarian cancer cells were exposed to different concentrations of CoCl2 (50, 100, 150 and 200 μM) for 48 h39." (PMID 36879003, 2023). "For example, baicalein is known to inhibit the expression of VEGF, HIF-1α, c-Myc or NF-κB in ovarian cancer cells, thereby inhibiting the metastatic potential of ovarian cancer cells, while the effect on normal cells is generally less." (PMID 36770705, 2023). "• Sevoflurane downregulated PEDF but upregulated the Erk pathway and HIF-1α, while propofol had the adverse effects on ovarian cancer cells." (PMID 36207479, 2023). "miR-138 has also been found dysregulated in various tumor types, notably RCC, ovarian cancer, and oral cancer; targeting HIF-1α, SOX2 and HIF-1α, or RhoC and ROCK2, respectively." (PMID 37369946, 2023). "AM is an upstream molecule of VEGF/HIF-1α that favored angiogenesis after upregulating both factors in CAOV3 epithelial ovarian cancer cells." (PMID 36980580, 2023). "Asparagus extract was also enriched in saponins, a class of compounds with the previously reported ability to inhibit HIF1α in ovarian cancer cells (ginsenosides) with eventual suppression of the Warburg effect." (PMID 36851057, 2023). "In ovarian cancer cells, the presence of IL-6 induces the expression of HIF-1α through the activation of STAT3." (PMID 37501379, 2023). "SIK2 induces the Warburg effect in ovarian cancer cells by upregulating HIF-1a expression, through activation of the PI3K/AKT signaling pathway." (PMID 37508561, 2023). "A recent study indicated the antimetastatic effect of metformin on ovarian cancer by inhibiting mTOR-mediated HIF-1α activation." (PMID 37760498, 2023). "Our data indicated that, unlike the pro-tumor property of sevoflurane, propofol negatively modulated PEDF/Erk/HIF-1α cellular signaling pathway and inhibited ovarian cancer metabolic efficiency and survival, and hence decreased malignancy." (PMID 36207479, 2023). "The expression of HIF-1α was increased when primary ovarian cancer cells were cultured in media supplemented with 20% (v/v) of FCS and exposed to CoCl2 at concentrations ranging from 100 to 150 μM." (PMID 36879003, 2023). "The expression of HFE, MTF1, and BMP6 involved in iron regulation was associated with improved PFS in ovarian cancer, whereas the expression of HIF1A, GPI, and HAMP involved in this process was associated with poor PFS in ovarian cancer." (PMID 38186569, 2023). "In vitro and in vivo, CDKN2B‐AS1 interacts with miR‐411‐3p to regulate ovarian cancer through the HIF‐1a/VEGF/P38 pathway." (PMID 36525280, 2023). "LPA derived from ovarian cancer cells promotes the differentiation of fibroblasts into CAFs through a hypoxia-inducible factor 1 alpha (HIF-1α)-dependent mechanism." (PMID 36831623, 2023). "Studies have found that HIF-1α silencing can attenuate the viability of hypoxic ovarian cancer cells and increase apoptosis and autophagy through the PI3K/AKT/mTOR signaling pathway." (PMID 36523985, 2022).